MAP3K10 (mitogen-activated protein kinase kinase kinase 10)
Description:
Activates the JUN N-terminal pathway.
Synonyms: MLK2; MST; MEKK10
Tractability: Small molecule: a drug acting on it is in phase 2 or 3 trials; a high-quality ligand is known; it belongs to a druggable protein family. PROTAC: a small molecule that binds it is known.
Target class: TKL protein kinase group; Protein Kinase; Enzyme; TKL protein kinase MLK family; Kinase; TKL protein kinase MLK subfamily
Chemical probes: URMC-099
Gene: Protein-coding gene on chromosome 19 (40,191,426 to 40,215,578, forward strand). Ensembl gene ENSG00000130758.
Subcellular location (Human Protein Atlas): Actin filaments; Cytosol; Nucleoplasm
Gene Ontology:
Molecular function: bHLH transcription factor binding; protein binding; protein serine/threonine kinase activity; JUN kinase kinase kinase activity; protein kinase activity; transcription corepressor activity; ATP binding; MAP kinase kinase kinase activity; protein serine kinase activity
Biological process: negative regulation of transcription by RNA polymerase II; positive regulation of JNK cascade; smoothened signaling pathway; apoptotic process; JNK cascade; negative regulation of DNA-templated transcription; positive regulation of apoptotic process
Cellular component: cytoplasm
Genetic constraint (gnomAD): Loss-of-function variants: 22 observed, 62.14 expected, observed/expected ratio (o/e) 0.35, 90% interval 0.25 to 0.51. The upper end of that interval is the gene's LOEUF score, 0.51, which puts it in group 2 of 6, group 1 being the genes least tolerant of losing a copy. Missense variants: 1,145 observed, 1,206.5 expected, observed/expected ratio (o/e) 0.95, 90% interval 0.9 to 1. Synonymous variants: 590 observed, 537.55 expected, observed/expected ratio (o/e) 1.1, 90% interval 1.02 to 1.17.
Homologues: Orthologues: chimpanzee MAP3K10 (99% identical), macaque MAP3K10 (99% identical), pig MAP3K10 (94% identical), dog MAP3K10 (93% identical), mouse Map3k10 (92% identical), rat Map3k10 (92% identical), rabbit MAP3K10 (91% identical), guinea pig MAP3K10 (82% identical), tropical clawed frog map3k10 (64% identical), zebrafish map3k10 (63% identical). Paralogues in human: MAP3K9 (59% identical), MAP3K21 (48% identical), MAP3K11 (42% identical), MAP3K13 (24% identical), MAP3K12 (23% identical), MAP3K20 (15% identical), TNNI3K (14% identical), LRRK2 (13% identical), BRAF (13% identical), TESK1 (13% identical), ARAF (13% identical), RAF1 (12% identical), and 11 more.
Diseases named in the same sentence as MAP3K10 in open-access papers:
MAP3K10 is named in the same sentence as 18 diseases in open-access papers, as found by Europe PMC text mining. Sharing a sentence is not in itself a finding about the gene and the disease. The quoted sentences say what the papers report.
atherosclerosis (4 papers, 2016 to 2023). A disease characterized by the build-up of fatty material and calcium deposition in the arterial wall resulting in partial or complete occlusion of the arterial lumen. "They believed that increased miRNA-155 contributed to the prevention of atherosclerosis development via targeting mitogen-activated protein kinase kinase kinase 10 (MAP3K10)." (PMID 28018919, 2016). "Another study also showed that upregulated miR-155 in patients with CAD may inhibit atherosclerosis progression via targeting mitogen-activated protein kinase kinase kinase 10 (MAP3K10)." (PMID 28624816, 2017).
pancreatic cancer (2 papers, 2021 to 2023). "We also detected MAP3K10 expression in five pancreatic cancer cell lines and found MAP3K10 expression in all cell lines, but its level was significantly higher in Mia-paca-2(CSChigh) than in BxPC3 (CSClow)." (PMID 33995647, 2021). "MAP3K10 expression in pancreatic cancer is still unclear, so we first examined MAP3K10 in the 12 matched normal and cancer tissues by RT-PCR and western blot." (PMID 33995647, 2021). "MAP3K10 activity has been cited in many cancers, namely pancreatic cancer." (PMID 37759668, 2023). "To investigate whether miR-146b-3p affected P-CSCs through the Hh pathway, a crucial role for activated Shh signaling in pancreatic cancer (stem) cells, we choose MAP3K10 as the potential targeted gene." (PMID 33995647, 2021). "Thus, downregulated miR-146b-3p in pancreatic cancer inhibits the suppression of MAP3K10, which may in turn accelerate growth and tumorigenesis." (PMID 33995647, 2021).
aneurysm (1 paper, 2025). Bulging or ballooning in an area of an artery secondary to arterial wall weakening. "Hypomethylation of several genes, including CXCR4, OSM, GSTA4, MAP3K10, ADAMTS, PTBP1, and PNPLA6,61, –63,65,67,71 has been identified as being associated with the aneurysm formation." (PMID 41342741, 2025).
colon cancer (1 paper, 2014). "Fifteen genes (DUSP2, INFGR1, IL6, IRF2, JAK2, MAP3K10, MMP1, NFkB1A, NOS2A, PIK3CA, SEPX1, SMAD3, TLR2, TYK2, and VDR) were associated with colon cancer mortality (PARTP <0.05); JAK2 (PARTP = 0.0086), PIK3CA (PARTP = 0.0098), and SMAD3 (PARTP = 0.0059) had the strongest associations." (PMID 25541970, 2014). "Fifteen genes (DUSP2, INFGR1, IL6, IRF2, JAK2, MAP3K10, MMP1, NFkB1A, NOS2A, PIK3CA, SEPX1, SMAD3, TLR2, TYK2, and VDR) were significantly associated with colon cancer mortality at the <0.05 level; an additional 15 genes had gene PARTP values between 0.05 and 0.10." (PMID 25541970, 2014).
cancer (3 papers, 2021 to 2025). A tumor composed of atypical neoplastic, often pleomorphic cells that invade other tissues. "We found MAP3K10 can be detected in both cancer and matched normal tissues, but it was distinctly stronger in cancer tissues." (PMID 33995647, 2021).
tumor (2 papers, 2016 to 2022). "In this investigation, it was observed that MAP3K1, MAP3K3, MAP3K5, MAP3K10, and MAP3K15 were upregulated in HCC tumor tissues, whereas MAP3K7, MAP3K8, MAP3K9, and MAP3K11 were downregulated in tumor tissues in GSE14520." (PMID 35311629, 2022). "In this study using bioinformatic technology, we found that IL-6R, SOS-1, NF-IL-6, c-Fos, MAP3K10, NIK, SP1, MEF2, and other inflammatory factors and tumor regulatory molecules are also potential target genes of miRNA-155, but no definitive results have been reported yet." (PMID 27462776, 2016).
kidney disease (1 paper, 2021). "To this end, we selected three MAP3K genes, Ask1 (Map3k5), Mlk2 (Map3k10), and Mlk3 (Map3k11), with connections to kidney disease for further analysis." (PMID 34962918, 2021).
MAP3K10 also shares sentences with these, for which no sentence is quoted: glioblastoma (2 papers); leukemia (2); acute myeloid leukemia (1); anaplastic astrocytoma (1); cervical carcinoma (1); glioma (1); liver fibrosis (1); medulloblastoma (1); oligodendroglioma (1); osteoporosis (1); rheumatoid arthritis (1).